GIPR (gastric inhibitory polypeptide receptor)
Description:
This is a receptor for GIP. The activity of this receptor is mediated by G proteins which activate adenylyl cyclase.
Synonyms: PGQTL2
Tractability: Small molecule: a structure with a bound ligand is known; a high-quality ligand is known; it belongs to a druggable protein family. Antibody: UniProt places it where antibodies can reach, with high confidence; its Gene Ontology location is reachable by antibodies, with high confidence; UniProt predicts a signal peptide or a membrane-spanning region. PROTAC: a small molecule that binds it is known. Other modalities: an approved drug acts on it.
Target class: Glucagon-like receptor; Family B G protein-coupled receptor; Membrane receptor; Peptide receptor (family B GPCR); Gastric inhibitory polypeptide receptor
Safety:
Unwanted effects reported when the protein is acted on. In parentheses: how it was acted on, where the effect was seen, and who reports it.
plasma insulin levels (source: ClinPGx)
plasma insulin levels and weight gain (source: ClinPGx)
weight gain (source: ClinPGx)
Gene: Protein-coding gene on chromosome 19 (45,668,221 to 45,683,722, forward strand). Ensembl gene ENSG00000010310.
Subcellular location: Cell membrane
Subcellular location (Human Protein Atlas): Vesicles
Pathways (Reactome):
Signal Transduction: G alpha (s) signalling events; Glucagon-type ligand receptors
Gene Ontology:
Molecular function: gastric inhibitory peptide receptor activity; glucagon family peptide binding; peptide hormone binding; protein binding; G protein-coupled peptide receptor activity; transmembrane signaling receptor activity; G protein-coupled receptor activity
Biological process: adenylate cyclase-activating G protein-coupled receptor signaling pathway; gastric inhibitory peptide signaling pathway; activation of adenylate cyclase activity; adenylate cyclase-modulating G protein-coupled receptor signaling pathway; cell surface receptor signaling pathway; generation of precursor metabolites and energy; regulation of insulin secretion; response to nutrient; desensitization of G protein-coupled receptor signaling pathway; G protein-coupled receptor signaling pathway; positive regulation of cytosolic calcium ion concentration; positive regulation of insulin secretion; response to axon injury; response to calcium ion; response to fatty acid; response to glucose
Cellular component: membrane; plasma membrane
Genetic constraint (gnomAD): Loss-of-function variants: 60 observed, 45.41 expected, observed/expected ratio (o/e) 1.32, 90% interval 1.07 to 1.64. The upper end of that interval is the gene's LOEUF score, 1.64, which puts it in group 6 of 6, group 1 being the genes least tolerant of losing a copy. Missense variants: 597 observed, 523.31 expected, observed/expected ratio (o/e) 1.14, 90% interval 1.07 to 1.22. Synonymous variants: 233 observed, 227.7 expected, observed/expected ratio (o/e) 1.02, 90% interval 0.92 to 1.14.
Homologues: Orthologues: chimpanzee GIPR (99% identical), macaque GIPR (97% identical), pig GIPR (86% identical), rabbit GIPR (85% identical), guinea pig GIPR (83% identical), rat Gipr (79% identical), mouse Gipr (79% identical), dog GIPR (68% identical). Paralogues in human: GCGR (49% identical), GLP1R (43% identical), GLP2R (40% identical), SCTR (35% identical), VIPR1 (34% identical), PTH1R (34% identical), VIPR2 (32% identical), ADCYAP1R1 (32% identical), PTH2R (31% identical), GHRHR (27% identical), CALCRL (26% identical), CALCR (25% identical), and 30 more.
Diseases named in the same sentence as GIPR in open-access papers:
GIPR is named in the same sentence as 92 diseases in open-access papers, as found by Europe PMC text mining. Sharing a sentence is not in itself a finding about the gene and the disease. The quoted sentences say what the papers report.
Obesity (151 papers, 2008 to 2026). Accumulation of substantial excess body fat. "A clear limitation of this study is that it is unlikely that a GIPR agonist or antagonist will be given alone for the treatment of obesity/diabetes as weight loss is modest compared to GLP‐1R agonism." (PMID 41287212, 2026). "Both GIPR knockout mice and GIP over‐expressing mice are protected from high‐fat diet–induced obesity, and both GIPR agonists and GIPR antagonists induce moderate weight loss in preclinical obesity models." (PMID 41287212, 2026). "In support of this idea, Gipr−/− knock-out mice are resistant to obesity on high-fat diets, and low-frequency loss-of-function mutations in the human GIPR gene have been linked to leanness and impaired bone strength." (PMID 41528263, 2026). "For GIPR agonism, genetically proxied lower BMI via GIPR showed a robust association with reduced obesity risk, with highly similar effect sizes across the two exposure datasets." (PMID 40931165, 2025). "GIP-induced vasodilation is blunted in adipose tissue of people living with obesity and insulin resistance, and in healthy humans upon antagonism of GIPR, and normalizes upon weight loss and restoration of insulin sensitivity." (PMID 40024571, 2025). "Incretin receptor agonists including GLP-1R agonists and dual GLP-1R/GIPR co-agonists reduce food intake and drive weight loss in patients with obesity." (PMID 39963285, 2025). "Although the exact mechanism underlying the anti-obesity effect of GIP or the GIPR system is unclear, cumulative results support that the therapeutic effect associated with the modulation of the GIP system is mediated by the central nervous system (CNS)." (PMID 39940910, 2025). "For example, GLP-1R/GIPR dual agonists have demonstrated superior glucose-lowering and weight-loss effects in the treatment of diabetes and obesity." (PMID 40520185, 2025). "One study linked the anti-obesity effect of GIPR antagonism to leptin sensitivity in the hypothalamus, where genetically or pharmacologically blocking GIPR enhanced the anorexigenic properties of leptin in HFD-fed mice." (PMID 40166681, 2025). "Similar to animal studies with deletion of the GIPR gene that exhibit protection toward obesity, early genome-wide association studies (GWAS) in humans have revealed the GIPR gene to be associated with BMI." (PMID 40469445, 2025). "Based on these mouse and human genetic associations, GIPR antagonism has been explored as a therapy to treat obesity." (PMID 39114288, 2024). "In 2014, Mallafre reported that signaling of glucose-dependent insulinotropic peptide (GIP) and its receptor (GIPR) played key roles in the pathogenesis of obesity and its associated insulin resistance." (PMID 35721732, 2022). "According to our earlier data, a special role in the disturbance of carbohydrate metabolism in obesity is played by the occurrence of polymorphisms in the GIPR and GLP-1R genes." (PMID 33959145, 2021). "Genome-wide association studies (GWAS) have revealed that common variants in the GIPR are associated with obesity and impaired glucose- and bone mineral homeostasis." (PMID 34760890, 2021). "The present study showed the participants with high PRS of appetite-related genes, mainly MC4R pathway-related genes, including SEC16B_ rs543874, BDNF_ rs6265 DNAJC27_ rs713586, MC4R_rs17782313, GIPR_ rs1444988703, increased the obesity risk by 1.6-fold." (PMID 34836030, 2021). "In conclusion, a PRS model using SEC16B_rs543874, DNAJC27_rs713586, BDNF_rs6265, MC4R_ rs6567160, and GIPR_rs1444988703 had gene−gene interactions which elevated the obesity risk." (PMID 34836030, 2021). "GIPR is linked to obesity and several obesity-related traits, including body mass index and type 2 diabetes." (PMID 27934696, 2016). "Despite all evidence for the involvement and importance of GIPR in obesity, until now few studies analysed variants in GIPR and their risk for obesity." (PMID 19254363, 2009).
Obesity (continued). "Analyses of the putative regulatory region of GIPR were previously performed in patients with Cushing syndrome, which is associated with obesity." (PMID 19254363, 2009). "We provide evidence for an association of polymorphisms in and near the GIPR gene with obesity or increased BMI." (PMID 19254363, 2009). "In conclusion, our data provide a first step towards identification of GIPR variants potentially involved in obesity." (PMID 19254363, 2009). "Recently, GIP receptor-deficient mice (GIPR−/−) were shown to be completely protected from diet-induced obesity." (PMID 18779862, 2008). "In fact GIP receptor-deficient mice (GIPR−/−) were shown to be completely protected from diet-induced obesity." (PMID 18779862, 2008). "By contrast, other studies have shown that global GIPR-KO mice are protected from both obesity and insulin resistance when fed a high-fat diet, and GIPR antagonism coupled with GLP-1R agonism leads to weight loss in early clinical trials and mouse models, possibly by preventing leptin resistance." (PMID 40857106, 2025). "Alternatively, the monomeric compound, tirzepatide (ZepboundTM), targets both GLP-1R and glucose-dependent insulinotropic polypeptide receptor (GIPR), and was recently reported to elicit 20.9% and 25.3% weight loss in humans with obesity over 72- and 88-week trials." (PMID 39502365, 2025). "Genetic evidence, such as GWAS, has identified the single-nucleotide polymorphism (SNP) in GIPR, showing that lower function of GIPR is associated with lower BMI, allowing speculation that higher GIPR activity is obesity promoting." (PMID 39114288, 2024). "Recent research has surprisingly indicated that both agonists and antagonists of GIPR may be useful in the treatment of obesity and type 2 diabetes, as both result in weight loss when combined with GLP-1 receptor activation." (PMID 34760890, 2021). "Therefore, GIP receptor (GIPR) antagonists were initially developed to induce weight loss and to control glycaemia levels in obesity and individuals with T2DM." (PMID 34072172, 2021). "Moreover, in healthy individuals, GIPR has been identified in multiple genome wide association studies as a contributing factor to obesity in European populations." (PMID 33788878, 2021). "In addition, the rs2268641 (C>T) SNP of GLP1R was associated with obesity in European Americans, and GIPR SNP rs2334255 (G>T) was identified as a novel common variant associated with both obesity and T2DM risk." (PMID 33503878, 2021). "The mechanisms explaining how GIPR single nucleotide variants influence obesity-related traits remain uncertain; however, it is probable that GIPR genetic variants have an impact on the ability of the receptor to stimulate adipogenesis and fat uptake or influence appetite." (PMID 33503878, 2021). "GIPR deficiency seems to prevent ovariectomy-induced obesity, which might be linked to the reduced expression of NPY in the hypothalamus and subsequent reduction of food intake." (PMID 26075286, 2015). "Our data suggest a potential relevance of GIPR variants for obesity." (PMID 19254363, 2009). "However, the exact mechanism underlying the anti-obesity effect of GIP or the GIPR system remains unclear." (PMID 39940910, 2025). "Hence, diminishing the activity of GIPR may be a way to treat obesity as individuals who carry these variants have considerably lower BMI than the general population." (PMID 38118020, 2024). "Here, we report the design and optimization of novel antibody-peptide conjugates that combine glucose-dependent insulinotropic polypeptide receptor (GIPR) antagonism with glucagon-like peptide 1 (GLP-1) receptor (GLP-1R) agonism for the treatment of obesity." (PMID 41941715, 2026). "Tirzepatide, a dual agonist of the glucagon-like peptide 1 receptor (GLP-1R) and glucose-dependent insulinotropic polypeptide receptor (GIPR), represents a new class of medication for obesity and type II diabetes treatment." (PMID 42219687, 2026).
Obesity (continued). "Among these, tirzepatide, a long-acting dual GLP-1R/GIPR agonist approved for diabetes and obesity, shows enhanced therapeutic outcomes on cardiometabolic diseases compared to selective GLP-1R agonists." (PMID 41506148, 2026). "The mechanisms of action of these therapies and the role of endogenous incretins are active areas of research, particularly considering the controversies surrounding agonism/antagonism of GIPR as potential treatments for obesity." (PMID 41528263, 2026). "Multi-target peptide therapeutics targeting glucagon receptor (GCGR), glucagon-like peptide-1 receptor (GLP1R), and glucose-dependent insulinotropic polypeptide receptor (GIPR) represent a promising approach for treating diabetes and obesity." (PMID 41333850, 2025). "A centrally administered antibody neutralizing GIPR reportedly reduced body weight and adiposity in mice with diet-induced obesity." (PMID 39940910, 2025). "There is renewed interest in targeting the glucose-dependent insulinotropic polypeptide receptor (GIPR) for treatment of obesity and type 2 diabetes." (PMID 39788289, 2025). "And yet, undeterred, dual agonism of GLP-1R and GIPR has also progressed and, in fact, achieved regulatory approval first for both T2D and obesity indications in the form of unimolecular co-agonist tirzepatide." (PMID 40507574, 2025). "Several groups are developing GIPR antagonists for the treatment of obesity, as discussed in more detail below." (PMID 40166681, 2025). "Specifically, BMI-lowering relationships via GLP1R and GIPR loci appear to be predominantly mediated through CNS-driven behavioral regulation, influencing binge drinking, food preferences, and obesity." (PMID 40931165, 2025). "The role of GIP signaling in glucose-mediated AgRP neuron inhibition is consistent with the anorexigenic effects and obesity treatment efficacy of GIPR agonists." (PMID 40857106, 2025). "This appears analogous to the paradoxically similar abilities of GIPR agonist treatment and genetic invalidation of GIPR to protect mice against diet-induced obesity." (PMID 40892365, 2025). "Most recently, pharmaceutical companies have developed anti‐diabetic treatment through anti‐obesity approaches like GLP‐1R agonists or co‐agonists for glucose‐dependent insulinotropic polypeptide receptor (GIPR) and GLP‐1R." (PMID 41208560, 2025). "Several preclinical and clinical data suggest a role for GIPR agonism, as seen in dual GLP-1/GIPR agonists, in enhancing energy expenditure as part of their anti-obesity effects." (PMID 40892365, 2025). "The numerous beneficial effects of GIPR signal modification render the peptide an interesting candidate for the development of pharmacotherapies to treat obesity, diabetes, drug-induced nausea and both bone and neurodegenerative disorders." (PMID 40024571, 2025). "Both hormones also regulate food intake, and the success of GLP1R agonists and dual GLP1R/GIPR agonists in the treatment of obesity has kindled ongoing research to better understand which target cells are most relevant for these pharmacological outcomes." (PMID 39576749, 2025). "The physiologic and pathophysiologic role of GIP as an adipogenic factor in humans provides an initial rationale for the development of GIPR antagonists to treat obesity." (PMID 40507574, 2025). "AMG133, a bispecific hybrid that comprises two GLP-1R agonists conjugated to a monoclonal anti-GIPR antagonist is currently in phase 2 clinical development for the treatment of obesity and type 2 diabetes." (PMID 40301583, 2025). "There has been great interest in targeting the glucose-dependent insulinotropic polypeptide receptor (GIPR) as a means of augmenting the insulinotropic and anti-obesity action of glucagon-like peptide-1 receptor (GLP-1R) agonists." (PMID 39788289, 2025). "The GIP-GIP receptor (GIPR) system is known to significantly contribute to the development of obesity." (PMID 39940910, 2025).
Obesity (continued). "Recently, clinical trials of tirzepatide, a dual GLP-1R and glucose-dependent insulinotropic polypeptide receptor (GIPR) agonist, have achieved approximately 20% weight loss in substantial proportions of people with obesity." (PMID 41178710, 2025). "As the first anti-obesity drug targeting multiple receptors, tirzepatide (Zepbound®, Eli Lilly), a dual GIPR/GLP-1R agonist, was approved by the FDA in 2022." (PMID 40607142, 2025). "However, how GIPR inhibition protects from obesity and associated insulin resistance remains puzzling, and may include increased lipid utilization, decreased intestinal nutrient uptake [1023], decreased food intake [805,1008], and/or increased energy expenditure." (PMID 40024571, 2025). "As apparent from the parallel development of drugs combining GLP1R agonism with either GIPR agonists or antagonists for the treatment of obesity, GIP appears to have several, sometimes opposing, actions on the brain." (PMID 40166681, 2025). "It is therefore counterintuitive that GIPR signal inhibition also shows clear benefit in obesity and T2D." (PMID 40024571, 2025). "The therapeutic potential of glucagon-like peptide-1 receptor agonists (GLP1RAs), such as semaglutide, and dual GIP receptor (GIPR)/GLP1RAs, like tirzepatide, extends beyond metabolic diseases like diabetes and obesity." (PMID 40931165, 2025). "Central administration of GIPR-neutralizing antibody showed anti-obesity effects in diet-induced obese mice." (PMID 39940910, 2025). "The blunted weight-reducing effect of intracerebroventricular administered acyl-GIP in the brain-specific GIPR knockout mice indicates that the anti-obesity effect of GIP or the GIPR system is mediated via GIPR in the CNS." (PMID 39940910, 2025). "GIPR agonists administered at an increased frequency and for an extended duration decreased body weight in mice with diet-induced obesity." (PMID 39940910, 2025). "Such agents are now well-established for treating obesity and T2D in humans, and therapies combining GIPR antagonism with GLP-1R agonism have also shown promising results in clinical studies." (PMID 40024571, 2025). "There was an upsurge of GIP focused research since the extended-release GLP-1R and GIPR co-agonist tirzepatide became available for T2D and obesity treatment." (PMID 40687579, 2025). "While these data do not speak directly to the potential efficacy of GIPR antagonists as weight reducing pharmacologic agents, they do provide a deterrent from developing GIPR agonists for T2D and obesity." (PMID 40507574, 2025). "The physiologic role of GIP to regulate prandial glucose and lipid metabolism coupled with numerous preclinical studies commend GIPR antagonism as the appropriate mechanism to treat obesity." (PMID 40507574, 2025). "The receptors of the moment, however, and of broadest societal relevance, are the incretin hormone receptors, GLP1R and GIPR—both key targets for anti-obesity therapy development." (PMID 39910307, 2025). "Incretin‐based therapies using single agonists towards GLP‐1 receptor (GLP‐1R) or GIP receptor (GIPR) and dual agonists towards GLP‐1R/GIPR have proven to be effective therapeutic options in type 2 diabetes (T2D), obesity, and related CVDs." (PMID 40838278, 2025). "Tirzepatide, an imbalanced dual agonist of GLP‐1R/GIPR, has been approved for therapy in both T2D and obesity." (PMID 40838278, 2025). "GLP-1R, GCGR and GIPR are essential regulators of glucose homeostasis and therapeutic targets for type 2 diabetes and obesity." (PMID 38346960, 2024). "The combination of an anti-GIPR monoclonal antibody (mAb) and a GLP-1RA has been shown to mediate more pronounced weight loss than either agent alone in preclinical obesity models." (PMID 38316982, 2024). "Tirzepatide is the first FDA-approved GLP-1R/GIPR agonist for treating T2D and more recently approved for the treatment of overweight or obesity." (PMID 38477666, 2024).